APC (APC regulator of Wnt signaling pathway)
Diseases named in the same sentence as APC in open-access papers (continued):
Sharing a sentence is not in itself a finding about the gene and the disease.
colorectal tumors (continued). "In most colorectal tumours, APC mutation stabilises β-catenin and mimics elements of Wnt growth factor signalling, but the high frequency of epigenetic loss of Wnt antagonists indicates an additional role for ligand-mediated Wnt signalling." (PMID 18414471, 2008). "Biallelic germline mutations in MYH are associated with colorectal neoplasms, which develop through a pathway involving somatic inactivation of APC." (PMID 17031395, 2006). "The frequency of 37% of truncating mutations in the mutation cluster region of APC in this study, however, seems low in comparison to the general assumption that most colorectal tumours harbour a mutation in the APC gene." (PMID 16356174, 2005). "Intracellular redistribution of β-catenin through mutation of the adenomatous polyposis coli (APC) gene has been proposed as an early tumorigenic event in most colorectal tumours." (PMID 12838317, 2003). "Recently, mutation in exon 3 of β-catenin has been identified in approximately half of colorectal tumours that lack APC mutations." (PMID 12838317, 2003). "Recent experimental and clinical analyses have indicated that cytoplasmic expression and nuclear translocation of β-catenin in colorectal tumour cells usually results from mutations in the APC or β-catenin genes." (PMID 12838317, 2003). "Notably, there is a distinct APC mutation cluster region in duodenal adenomas compared with that observed in colorectal tumours and WTX mutations that were observed recurrently in exome sequencing of colorectal adenomas, were absent from duodenal adenomas." (PMID 38546397, 2024). "Chromosome instability has been observed in colorectal tumor cells by a dominant mutation in APC." (PMID 39021676, 2024). "Most colorectal tumors are initiated by mutation of APC, which drives Wnt signaling." (PMID 37902809, 2023). "Approximately 90% of sporadic colorectal tumors carry a mutation in APC." (PMID 37927787, 2023). "APC inhibits the Wnt signaling pathway, and loss-of-function mutations in APC lead to accumulation and nuclear translocation of β-catenin, resulting in aberrant upregulation of Wnt signaling and colorectal tumour initiation." (PMID 36263033, 2022). "Somatic APC mutations are found in more than 80% of sporadic colorectal tumors." (PMID 34162944, 2021). "Interestingly, APC and β-catenin mutations are mutually exclusive events and associate with different types of colorectal tumors." (PMID 32481626, 2020). "Additionally, we found a heterozygous nonsense mutation in APC and frameshift indels in known colorectal tumor suppressors; ATM, SOX9, RNF43, and ZFP36L2, of likely driver status." (PMID 32697969, 2020). "Similarly, the levels of Asef in the cytoplasm were also increased in colorectal tumor cells bearing APC mutations." (PMID 32178475, 2020). "Notably, the restoration of APC in APC-deficient colorectal tumors triggers cell differentiation and re-establishes intestinal homeostasis; thus, even late-stage tumors continue to rely on hyperactivated Wnt signaling to sustain their growth." (PMID 29615557, 2018). "Besides APC, we also investigated other genes with germline mutations involved in human colorectal tumor development." (PMID 30018743, 2018). "Colorectal tumors are dominated by APC mutations which almost always cause deletion of both central domains that interact with β-catenin and C-terminal domains that interact with the cytoskeleton and play a role in microtubule binding, cell polarity, and chromosome segregation." (PMID 27047543, 2016).
colorectal tumors (continued). "Interestingly, a small subgroup of colorectal tumors with wild-type APC has point mutations in β-catenin that allow it to escape degradation." (PMID 26134786, 2015). "Normal APC protein could downregulate the Wnt signaling pathway through its binding to β-catenin and Axin, but most mutated APC proteins in colorectal tumors fail to inhibit Wnt signaling, leading to the overproliferation of tumor cells." (PMID 21423639, 2011). "The constitutive Wnt signalling unleashed by this epigenetic event is believed to precede genetic alterations, i.e., mutations, in key components of the pathway, such as the APC gene, whose inactivation is traditionally considered the trigger of colorectal tumor progression." (PMID 20015382, 2009). "Although most colorectal tumours harbour APC mutations, some develop through alternative routes." (PMID 18414471, 2008). "Our results suggest that loss of HOXB13 may be an important event for colorectal cell transformation, considering that over 90% of colorectal tumours retain mutations in the APC/β-catenin pathway." (PMID 15928669, 2005). "In FAP, many colorectal tumors (57.5%) harbored two APC hits, whereas in sporadic cases, one or two hits were more common (44.4% and 22.2%, respectively)." (PMID 41488735, 2025). "This suggests that second hits in APC are selected to produce a ‘just-right’ level of β-catenin signaling optimal for colorectal tumor development." (PMID 41488735, 2025). "To achieve this goal, we performed genome-wide small-RNA sequencing of sporadic colorectal tumors in young patients (<50 years old) and old patients (>50 years old) negative for canonical CRC markers like MSI, nuclear β-catenin, and APC mutation." (PMID 39997610, 2025). "Mutant loci in APC appeared to be more widely distributed in the sporadic colorectal neoplasms than in neoplasms of FAP patients." (PMID 41488735, 2025). "The K-Ras gene is known to contribute to the inactivation of the tumor suppressor gene APC, marking a critical initial step in the development of most colorectal tumors." (PMID 40747299, 2025). "These acquired biallelic APC mutations are recognized as an early and rate limiting step in most sporadic colorectal tumors and all FAP-associated colorectal tumors." (PMID 38590663, 2024). "In mouse models, conditioned knockout of APC in Lgr5− cells inhibited the growth of intestinal adenomas, while conditional knockout of APC in Lgr5+ cells drove intestinal adenomas, proving that Lgr5+ cells are CSCs for colorectal tumors." (PMID 38254219, 2024). "APC mutation results in the growth disorder of intestinal epithelial cells, leading to the formation of CRC, and is an early event of colorectal tumors." (PMID 35736152, 2022). "In our study, the mRNA level of the APC gene was significantly decreased in all colorectal tumor tissues, while the peripheral blood of the same cases increased significantly." (PMID 33237662, 2021). "From a comparative point of view, in intestinal neoplasms in dogs, CTNNB1 mutations were proven to be more often causative than APC mutations, with CTNNB1 being mutated in >60% of canine colorectal tumors." (PMID 34885050, 2021). "According to their research, the truncated form of the APC protein stimulates the migration of colorectal tumor cells and promotes the development of chromosomal instability." (PMID 34769425, 2021). "Asef2 activated by truncated mutant APC is required for aberrant migration of colorectal tumor cells." (PMID 32178475, 2020).
colorectal tumors (continued). "Asef2 increases the levels of the active forms of Rac1 when co-transfected with truncated mutant APC expressed in colorectal tumor cells." (PMID 32178475, 2020). "WT Fusobacterium nucleatum significantly increased the number of colorectal tumors, tumor size (> 3 mm) and tumor burden in APC (Min/+) mice when compared with control mice." (PMID 32993749, 2020). "APC and KRAS mutations co-occurred in 10/152 (6.6%) of colorectal tumours, with a tendency towards mutual exclusivity." (PMID 32087721, 2020). "In summary, MSC2504877 is a novel, drug-like, tankyrase inhibitor that inhibits APC mutant colorectal tumour cells." (PMID 30655555, 2019). "Here, we describe here a novel, drug-like small molecule inhibitor of tankyrase MSC2504877 that inhibits the growth of APC mutant colorectal tumour cells." (PMID 30655555, 2019). "N14-77 polyps express a lower amount of APC_AS1, but the level is still higher than colorectal tumors with APC deletion." (PMID 30018743, 2018). "Colorectal tumour retains a truncated APC protein to control the transcriptional activity of β -catenin and avoids it to reach too high levels, which is detrimental for tumour growth, in agreement with the “just right signalling” model." (PMID 28576136, 2017). "Methylation of APC has been represented in a subset of colorectal tumors, but the exact role and density of this alteration, its functional consequences, and its tumor distribution need to be addressed in future." (PMID 28331559, 2017). "MYC levels further increase at the transition to frank lymphomas and there is clear evidence for further increases in MYC levels during progression of several tumor entities, as for example in APC-mutant colorectal tumors." (PMID 27460974, 2016). "APC also regulates cell proliferation of RAS induced ERK activation playing an important role in colorectal tumor suppression." (PMID 24943349, 2014). "APC stimulates the activity of the Cdc42- and Rac1-specific guanine nucleotide exchange factor Asef and promotes the migration and invasion of colorectal tumor cells." (PMID 24244701, 2013). "This provides a general rule explaining the retention of truncated APC in colorectal tumours and defines it as a suitable target for therapeutic intervention." (PMID 22509309, 2012). "We mapped mitotic recombination boundaries ("breakpoints") between the centromere (~50 Mb) and APC (~112 Mb) in early colorectal tumours." (PMID 19515250, 2009). "In this study, we set out to improve our understanding of mitotic recombination by characterising LOH breakpoints proximal to the APC locus in colorectal tumours." (PMID 19515250, 2009). "Hypermethylation of CpG sites in the promoter of APC has been reported as a means of gene silencing in colorectal tumors." (PMID 18433509, 2008). "We therefore examined the distribution of endogenous APC in the human colorectal tumour cell lines Caco-2 and SW480." (PMID 16423286, 2006). "The early to intermediate stages of the majority of colorectal tumours are thought to be driven by aberrations in the Wnt (APC, CTNNB1) and Ras (K-ras) pathways." (PMID 16356174, 2005). "An alternative mechanism to inactivate the gene in colorectal tumors is by promoter methylation, and we report a frequency of APC methylation in the upper range of what has been seen in previous studies." (PMID 15476557, 2004). "Inactivation of the adenomatous polyposis coli (APC) suppressor gene is an initial event in the development of most colorectal tumours." (PMID 12838317, 2003).
colorectal tumors (continued). "We performed an RNA-Seq analysis of sporadic colorectal tumors in young patients (EOCRC < 50 years old) and aged patients (LOCRC > 50 years old) negative for canonical CRC markers like MSI, nuclear β-catenin, and APC mutation." (PMID 39997610, 2025). "Moreover, APC can inhibit the initiation and development of colorectal tumor, independently of canonical Wnt signaling." (PMID 39200196, 2024). "Thus, targeting the APC gene is helpful in the prevention and treatment of colorectal tumors, and APCMin/+ transgenic mice are the classic model for studying the occurrence and development of intestinal tumors." (PMID 35736152, 2022). "Moreover, the frequencies of APC or CDKN2A gene abnormalities in SIT are significantly lower than those in colorectal tumors." (PMID 35566730, 2022). "In addition to LRP5/6, the role of the truncated form of the APC protein in colorectal tumor was also established by Schneikert and Behrens." (PMID 34769425, 2021). "Recurrent LINE1 insertions into the APC locus are thought to initiate colorectal tumor development." (PMID 33802828, 2021). "The majority of the reported somatic and germline APC variants in CMV-PTC, were not within the mutation cluster region (MCR) in APC (codons 1286–1513) for somatic mutations in colorectal tumors." (PMID 31598872, 2020). "In conclusion, common colorectal tumour risk alleles contribute to the development of multiple adenomas in patients without pathogenic germline APC or MUTYH variants." (PMID 24801760, 2015). "Therefore, we have analyzed an extended region of the APC gene in DNA extracted from tumours removed from Ashkenazim carrying c.3920T>A, and for whom DNA was available from multiple colorectal tumours." (PMID 24416237, 2014). "In this context, it is interesting to note that CGI methylation has only a limited effect on the expression of APC in human colorectal tumours, and consequently the role of APC methylation in carcinogenesis remains unclear." (PMID 23157586, 2013). "Our work confirms that EB1 and APC have important mitotic roles, the loss of which could contribute to CIN in colorectal tumour cells." (PMID 22216133, 2011). "The defects identified in our studies are consistent with important mitotic roles for APC and EB1, the loss of which could contribute to CIN in colorectal tumour cells." (PMID 22216133, 2011). "Accordingly, allelic loss of one APC gene copy without detectable APC mutation has been reported in human colorectal tumours." (PMID 20459814, 2010). "Our results indicate that MCC is unlikely a player in early colorectal tumorigenesis, and we hypothesize that its disruption in human colorectal tumors is most likely a mere result of its close proximity to APC in the human genome." (PMID 20707908, 2010). "LOH on 5q is non-random, but local factors do not greatly influence the rate of LOH at APC or explain inter differential susceptibility to colorectal tumours." (PMID 19515250, 2009). "However, APC and β-catenin mutations are generally mutually exclusive, with somatic APC mutations being found in more than 80% of sporadic colorectal tumors and β-catenin mutations in about 48% of tumors without APC mutation." (PMID 36432565, 2022).
colorectal tumors (continued). "Consistent with previous reports, the levels of cytoplasmic APC in colorectal tumor cells harboring an APC mutation (SW480, SW620, HT29, Caco-2 and LoVo cells) were significantly higher than those in MDCK II and colorectal tumor cells with wild-type APC (HCT116 and SW48 cells)." (PMID 32178475, 2020). "To assess whether this selectivity could also be achieved in colorectal tumour cell lines with naturally occurring APC gene mutations, we assessed the effect of MSC2504877 in APC mutant (p.S811* homozygous) COLO320DM and APC wild type RKO colorectal tumour cell lines." (PMID 30655555, 2019). "Taken together these findings, as well as the previous extensive knowledge of the tumor-initiating role of APC in most CRCs33,34, suggest that retrotransposon insertions may have contributed to the early steps of tumorigenesis in 2 of the 202 colorectal tumor patients." (PMID 31492840, 2019). "Indeed, APC mutations in colorectal tumors are distributed non-randomly within the gene, with the position and type of the somatic APC mutation depending on the germline mutation." (PMID 28010732, 2016). "Additionally, we observed a similar, though less pronounced, repressive effect of GRG5/AES in DLD-1, a colorectal tumor cell line which displays constitutive TCF4-β-catenin dependent transcription due to APC mutations (data not shown)." (PMID 23840876, 2013). "Furthermore, a number of studies have found APC to be localised apically with a range of independent antibodies directed to both the amino and carboxy terminus of APC in a variety of different cell lines and human and mouse tissues, including normal colon and colorectal tumours." (PMID 17595655, 2007). "The stabilization and nuclear translocation of TIAM1 following APC depletion was also confirmed by immunofluorescence microscopy and is consistent with the nuclear accumulation of TIAM1 we observe in colorectal tumors and CRC cell lines with defective APC." (PMID 28416184, 2017). "In the situation where tumors are homozygous mutant for APC, the site of the “first hit” in the APC gene determines the type of the “second hit,” both in hereditary (FAP) and sporadic colorectal tumors." (PMID 24224156, 2013). "Thus, it is tempting to hypothesize that colorectal tumours always retain a truncated APC product to still keep a control over the transcriptional activity of β-catenin and avoid it to reach a level too high, detrimental for tumour growth, in accordance with the “just right signalling” model." (PMID 22509309, 2012). "Colorectal tumors of FAP and non-polyposis patients showed a similar frequency of mutations (APC, 76% and 75%; KRAS, 32% and 25%)." (PMID 41488735, 2025). "For example, the frequencies of APC and CDKN2A gene abnormalities in small intestinal adenocarcinoma are lower than in colorectal cancer, but KRAS gene abnormalities are observed as frequently as in colorectal tumors." (PMID 35566730, 2022). "While APC gene mutations are found in a large proportion of colorectal tumors and are tightly related to WNT hyperactivity, no particular patterns were observed between APC-mutated cases and G9a mutations or expression." (PMID 32512705, 2020). "First, signature genes characteristic of the tumor types in question, such as APC in colorectal tumors and ARID1A, PIK3CA, and PTEN in non-serous ovarian carcinomas were well represented." (PMID 29296220, 2017).